UGT1A1 (UDP glucuronosyltransferase family 1 member A1)
Diseases named in the same sentence as UGT1A1 in open-access papers (continued):
Sharing a sentence is not in itself a finding about the gene and the disease.
Hyperbilirubinemia (continued). "First, although a meta-analysis has elucidated the association of neonatal hyperbilirubinemia with UGT1A1 promoter variations, we did not explore the promoter region in our study due to the unavailability of clinical exome sequencing data for reanalysis." (PMID 38274110, 2023). "Previous studies conducted in Asia, often comparing neonates with hyperbilirubinemia to a control group without hyperbilirubinemia, have identified UGT1A1*6 (c.211G>T) and UGT1A1*28 [A(TA)7TAA] as two common variants associated with hyperbilirubinemia." (PMID 38274110, 2023). "Transgenic mice that are homozygous for the human UGT1A1*28 (HuUGT*28) exhibit moderate hyperbilirubinemia and are protected against the development of dietary-induced hepatic steatosis via decreased serine 73 phosphorylation, an inhibitory site of the PPARα protein." (PMID 36830621, 2023). "In this genetic association study of 3557 children, adolescents, and young adults receiving ALL therapy, variants in UGT1A1 and PNPLA3 were associated with hyperbilirubinemia and elevated alanine aminotransferase and aspartate aminotransferase levels, respectively." (PMID 36580335, 2022). "Crigler-Najjar syndrome type 1 is the most severe form of this autosomal recessive condition, characterized by non-hemolytic unconjugated hyperbilirubinemia associated with the absence of hepatic UGT1A1 activity." (PMID 36499207, 2022). "Our study was also limited to only two genes, SLCO1B1 and UGT1A1, so other genes related with hyperbilirubinemia could be investigated in further studies." (PMID 35501760, 2022). "To date, two UGT1A1 genetic variants (rs4148323 and rs3064744) have been associated with neonatal hyperbilirubinemia; however, the direct association between UGT1A1 variants and Bf levels in newborns has not been elucidated." (PMID 36293671, 2022). "Individuals who are UGT1A1 PMs (e.g., UGT1A1 *28/*28, UGT1A1 *6/*6) may display mild hyperbilirubinemia, referred to as Gilbert’s syndrome." (PMID 33805415, 2021). "Furthermore, UGT1A1 PMs were more likely to develop high-grade hyperbilirubinemia at lower serum concentrations of nilotinib." (PMID 33805415, 2021). "Assessment of UGT1A1 *6,*27, and *28 alleles in 34 Japanese patients with CML receiving nilotinib found that UGT1A1 PMs (*6/*6, *6/*28, and *28/*28) had increased rates of hyperbilirubinemia and greater nilotinib dose reductions." (PMID 33805415, 2021). "The purpose of this study was to explore the relationship between neonatal hyperbilirubinemia and G6PD deficiency and to investigate the effect of G6PD deficiency and UGT1A1 variant on bilirubin level of icteric neonates in Chaozhou, eastern Guangdong Province." (PMID 34895177, 2021). "Regorafenib is also a potent UGTs inhibitor, which is consistent with the hypothesis that inhibition of UGT1A1 is involved in the hyperbilirubinemia observed in patients treated with this drug." (PMID 32585893, 2020). "Moreover, bilirubin-induced hyperbilirubinemia was more severe at ZT2 than ZT14 in wild-type mice consistent with lower expressions of Ugt1a1 and Mrp2 (two bilirubin detoxification proteins) at ZT2 than ZT14." (PMID 31410205, 2019). "The current study aimed to investigate the effects of uridine diphospho-glucuronosyl transferase 1A1 (UGT1A1) and/or solute carrier organic anion transporter family member 1B (SLCO1B) polymorphic variants and their combined effects on mild unconjugated hyperbilirubinemia in Chinese adults." (PMID 31737051, 2019). "However, the circadian time differences in hyperbilirubinemia ceased to exist in Bmal1-/- mice consistent with equal protein levels of Ugt1a1 (and Mrp2) at both circadian time points in the genetically modified mice." (PMID 31410205, 2019). "This study evaluated the UGT1A1 genotypes in hyperbilirubinemia patients from southeastern China." (PMID 31467903, 2019).
Hyperbilirubinemia (continued). "In summary, circadian clock has a dual role in regulating bilirubin detoxification, generating circadian variations in bilirubin level via direct transactivation of detoxifying genes Ugt1a1 and Mrp2, and defending the body against hyperbilirubinemia via Rev-erbα antagonism." (PMID 31410205, 2019). "Some neonatal hyperbilirubinemia and breast milk jaundice patients may belong to transient familial neonatal hyperbilirubinemia (OMIM#237900), which is related to UGT1A1 polymorphism or mutation." (PMID 30544479, 2018). "While for UGT1A1*60, there was no wild type detected in either group, small incidence of heterozygous form in high risk hyperbilirubinemia (13%), and higher incidence of homozygous form in low risk hyperbilirubinemia group (87–100%)." (PMID 29534743, 2018). "In high-risk hyperbilirubinemia neonates, the incidence of wild type (no risk for hyperbilirubinemia) was instead higher (40–36%) than UGT1A1*6 is (60–64%)." (PMID 29534743, 2018). "Crigler-Najjar syndrome (CNS) is an autosomal recessive disorder characterized by severe unconjugated hyperbilirubinemia caused by a deficiency of bilirubin glucuronidation, due to impaired or complete lack of UGT1A1 function." (PMID 28490767, 2017). "The findings suggest that a high incidence of neonatal hyperbilirubinemia in Taiwan may be derived from high prevalence of gene variants in G6PD, nt211 in UGT1A1, and HO-1 promoter GT-repeat." (PMID 27557546, 2016). "The log-binomial analysis demonstrated greater risks of hyperbilirubinemia in infants with GA at nt211 in UGT1A1 (RR = 1.548; 95 % CI = 1.096–2.187), short HO-1 promoter GT-repeat (RR = 2.185; 95 % CI = 1.527–3.125), and G6PD deficiency (RR = 1.985; 95 % CI = 1.010–3.901)." (PMID 27557546, 2016). "Similarly, sorafenib inhibits UGT1A1 bilirubin conjugation and phenotypically induce hyperbilirubinemia in patients with Gilbert’s syndrome." (PMID 26943680, 2016). "The activity of UGT1A1, the major enzyme responsible for bilirubin glucuronidation, is not detected in the foetal liver; it is induced after birth, which accounts for the onset of hyperbilirubinemia." (PMID 26652177, 2015). "However, Gilbert’s syndrome (GS, MIM*143500), an inherited form of mild hyperbilirubinemia, is typically caused by a homozygous TA insertion in the TATAA element of the 5’ promoter region in Europeans (normal A(TA)6TAA) (UGT1A1*28)." (PMID 26247603, 2015). "Thus, layered on a homozygous p.G71R UGT1A1 background, the additional ANK1 mutation appeared to cause hyperbilirubinemia." (PMID 26107955, 2015). "A retrospective case control study of breast-fed full-term infants was carried out to determine whether variants in Uridine Diphosphate Glucuronosyl Transferase 1A1 (UGT1A1) and Heme Oxygenase-1 (HMOX1) were associated with neonatal hyperbilirubinemia." (PMID 25102181, 2014). "Because nilotinib is a potent noncompetitive inhibitor of human UGT1A1 activity, the UGT1A1*28 polymorphism increases the risk of nilotinib induced-hyperbilirubinemia." (PMID 24650752, 2014). "Genotyping of UGT1A1 may be a supplementary method to predict the development of hyperbilirubinemia in breast-fed full-term Chinese infants." (PMID 25102181, 2014). "The OR for hyperbilirubinemia>40 μmol/L in patients with heterozygous UGT1A1*28 was increased 3 times over patients without this allele (OR 3.07, 95% CI 1.54-4.6) and 34 times as compared with homozygotes (OR 33.9, 95% CI 31.45-36.35)." (PMID 25394086, 2014). "The Elevation of unconjugated bilirubin due to inadequate bilirubin glucoronidation is associated with the accumulation of serum bilirubin, this unconjugated hyperbilirubinemia results from decreased activity of UGT1A1 enzyme to approximately 30% of normal levels." (PMID 24204915, 2013). "As a result of chronic hemolysis, hyperbilirubinemia is often observed leading to the formation of pigment cholelithiasis which could be busted by the presence of UGT1A1 defects." (PMID 24167350, 2013).
Hyperbilirubinemia (continued). "However, in hUGT1/Pxr−/− mice, hyperbilirubinemia is greatly reduced due to induction of hepatic UGT1A1." (PMID 22371261, 2012). "Interestingly, the humanized mouse that contains the genetic variant HuUGT*28, which is analogous to the UGT1A1*28 mutation causing GS in humans, represents a genuine animal model for GS, given that it displays similar levels of mild constitutive UCB hyperbilirubinemia compared to GS subjects." (PMID 40243597, 2025). "Notably, some cases of neonatal hyperbilirubinemia and breast milk jaundice may be classified as transient familial neonatal hyperbilirubinemia (OMIM#237900), a condition associated with UGT1A1 gene polymorphisms or mutations." (PMID 41169420, 2025). "Additionally, UGT1A1 is responsible for bilirubin metabolism in the body, and inhibition of UGT1A1 activity by herbal medicines may lead to hyperbilirubinemia, especially when co-administered with UGT1A1-inhibiting ACDs (e.g. SOF)." (PMID 40624553, 2025). "Interestingly, T3 specifically decreases UGT1A1 expression in a dose-dependent manner in rat hepatocyte cultures, possibly leading to increased circulating unconjugated bilirubin levels and mild hyperbilirubinemia." (PMID 40243597, 2025). "Additionally, research has indicated that in childhood leukemia, the allele frequency of UGT1A1*6 was notably elevated in the hyperbilirubinemia cohort compared to the non-hyperbilirubinemia cohort, thereby heightening the likelihood of adverse outcomes." (PMID 38651155, 2024). "The UGT1A1 homozygous variant (211G > A), but not the variants 1941C > G (rs1042640) and 2042C > G (rs8330), has been shown to be associated with increased bilirubin in Han Chines unconjugated hyperbilirubinemia neonates." (PMID 38332122, 2024). "However, our results showed that UGT1A1*28 is not a risk factor for developing neonatal hyperbilirubinemia." (PMID 35501760, 2022). "Thus, prolonged unconjugated hyperbilirubinemia may develop in infants with UGT1A1*6 who are fed with breast milk." (PMID 36605758, 2022). "This association may caution clinicians to assess UGT1A1 variations for neonates with ABO hemolysis, and may aid in the identification of high-risk population, which is important for management and intervention of hazardous hyperbilirubinemia." (PMID 34074250, 2021). "Increasing evidence has demonstrated that up-regulation of hepatic and intestinal UGT1A1 may accelerate the metabolic clearance of bilirubin or other UGT1A1-substrates, which in turn, provide alternative therapeutic therapy for the treatment of hyperbilirubinaemia and drug-induced liver toxicity." (PMID 33628187, 2020). "The predictive power of BSEP and MRP2 inhibition was evaluated in only one study which concluded that the Rfree value of >1.1 for BSEP inhibition, in combination with a similar cut-off for OATP1B1 and UGT1A1 inhibition, could be useful in predicting hyperbilirubinemia." (PMID 32796590, 2020). "Interestingly, in Indonesia, UGT1A1 polymorphisms do not appear to be associated with differences in the severity of hyperbilirubinemia." (PMID 31440488, 2019). "This might be why not all neonates harboring the UGT1A1*28 polymorphism and with exclusive breastfeeding suffer from hyperbilirubinemia, and vice versa." (PMID 31440488, 2019). "From previous studies in Javanese Indonesians and Malays, which are anthropologically closely related with Bengkulu Indonesians, the frequency of mutation of UGT1A1*6 (0.015 and 0.014) is quite low and does not differ significantly between normal bilirubin level and hyperbilirubinemia neonates." (PMID 29534743, 2018). "Moreover, recent investigations have also found mild hyperbilirubinemia that can be induced by either enhancement of HO activity or partial inhibition of UGT1A1, which has therapeutic potential for delaying CKD progression and improving cardiovascular outcomes in this patient population." (PMID 30597982, 2018).
Hyperbilirubinemia (continued). "However, the number of cases in this study was small; thus, the possible involvement of UGT1A1 in post-hepatitis hyperbilirubinemia remains unclear." (PMID 29386646, 2018). "Therefore, the high incidence of neonatal hyperbilirubinemia in Bengkulu is not solely caused by UGT1A1*6 nor UGT1A1*60 polymorphism." (PMID 29534743, 2018). "Additionally, multivariate logistic regression analysis identified that the mutant genotype of rs4148323 in the UGT1A1 gene, ABO incompatibility, G6PD deficiency, and SS genotype at rs1805173 locus of the HO-1 gene were genetic risk factors of neonatal hyperbilirubinemia." (PMID 30298137, 2018). "In severe CNS-I, the absence of UGT1A1 enzyme activity lead to non-hemolytic unconjugated hyperbilirubinemia, marked jaundice and may cause bilirubin encephalopathy (kernicterus)." (PMID 25319636, 2014). "Thus, OATP1B1 or UGT1A1 are responsible for bilirubin conjugation, and it follows that a defect in the function of either may result in unconjugated hyperbilirubinemia." (PMID 24090270, 2013). "UGT1A1 catalyzes the conjugation of hepatic bilirubin and polymorphisms in the promoter region of UGT1A1 are associated with Gilbert's Syndrome (inherited mild, chronic, unconjugated hyperbilirubinemia in the absence of liver disease or overt hemolysis)." (PMID 21108851, 2010). "In newborn children and hUGT1 neonatal mice, the UGT1A1 gene is repressed in the liver leading to increases in TSB levels, which results in varying degrees of hyperbilirubinemia." (PMID 36720308, 2023). "For carriers of UGT1A1*28/*28, *28/*37, *37/*37, and −364 TT, the CPIC guidelines recommend counseling on the possibility of developing hyperbilirubinemia before the initiation of the therapy." (PMID 35745658, 2022). "Univariate logistic regression between UGT1A1*28 (TA7) and total bilirubin level >1.9 mg/dl (moderate and severe hyperbilirubinemia) in patients treated with atazanavir." (PMID 34093191, 2021). "In the present study, we evaluated the effects of UGT1A1 and SLCO1B on mild unconjugated hyperbilirubinemia in adults." (PMID 31737051, 2019). "Based on previous GWAS, our study investigated the UGT1A1 and SLCO1B genetic variation of Chinese adults with hyperbilirubinemia and emphatically explored the combined effects of multiple variants." (PMID 31737051, 2019). "If positive, that means hyperbilirubinemia has a protective effect on NAFLD and UGT1A1 gene can be used as a gene target for the treatment of NAFLD." (PMID 30619479, 2018). "Concerning the only case of grade 2 hyperbilirubinemia (>1.5–3.0 × ULN), it corresponds to a patient UGT1A1*28/*28 homozygous receiving ATV (and RAL) in combination." (PMID 29743555, 2018). "Ferrying a construct driving hepatocyte specific expression of UGT1A1, both AAV8 and AAV1 provided an efficient correction of hyperbilirubinemia." (PMID 24386104, 2013). "In neonatal hUGT1 mice, UGT1A1 expression controls the levels of TSB, with significant hyperbilirubinemia developing due to limited expression of hepatic UGT1A1." (PMID 22371261, 2012). "We recommend performing a genetic analysis of UGT1A1 in patients presenting with chemotherapy-induced hyperbilirubinemia with no signs of liver impairment." (PMID 39996891, 2025). "In CNS2, also known as Arias’ disease, UGT1A1 activity is reduced but not completely absent, leading to less severe hyperbilirubinemia, with levels below 20 mg/dL, though they can rise to 40 mg/dL during acute exacerbations." (PMID 39456788, 2024). "Still, due to the off‐targeted activity on UGT1A1 (IC50 of 1.1 μM), AG‐270 led to hyperbilirubinemia and may limit the dose escalation." (PMID 39309689, 2024). "CNS type 1 (CNS1) is the most severe form, characterized by severe unconjugated hyperbilirubinemia since birth due to the absence of hepatic uridine 5'-diphosphate glucuronyltransferase (UGT1A1) activity." (PMID 37928349, 2023).
Hyperbilirubinemia (continued). "In humans, there are few reports of the developmental properties of UGT1A1 in neonatal liver and virtually no information on the importance of intestinal UGT1A1 expression as a modulator of neonatal hyperbilirubinemia." (PMID 36720308, 2023). "Therefore, this study aims to explore the correlation between two genes, UGT1A1 and SLCO1B1, and hyperbilirubinemia in Thai neonates." (PMID 35501760, 2022). "Mutant mice are a good model to study CNS-I, as they do not express UGT1A1 and display neonatal hyperbilirubinemia." (PMID 36078055, 2022). "There were 808 cases of hyperbilirubinemia without G6PD deficiency, 49 cases were randomly selected for genotyping of UGT1A1, 22 cases were wild type, 21 cases were c.211G > A heterozygous mutation, 6 cases were homozygous mutation of c.211A/A." (PMID 34895177, 2021). "Because UGT1A1 is expressed at an earlier age in mice as compared to humans, neonatal hyperbilirubinemia normally does not occur in mice." (PMID 34045606, 2021). "Since rodents express UGT1A1 at an earlier age than humans, they normally do not exhibit neonatal hyperbilirubinemia." (PMID 34045606, 2021). "Gunn rats have a congenital unconjugated hyperbilirubinemia in the upper range of GS due to the absence of functional UDP-glucuronosyltransferase 1A1 (UGT1A1), which leads to impaired conjugation and elimination of UCB." (PMID 33762933, 2021). "In our previous studies, we have demonstrated the role of UGT1A1 in non-hemolytic unconjugated hyperbilirubinemia in Chinese newborns." (PMID 34074250, 2021). "No statistical difference of severe hyperbilirubinemia incidence was found between ABO HDNs with and without the UGT1A1 mutation (P > 0.05)." (PMID 34074250, 2021). "We identified 136 publications appearing between 1996 and 2018 that genotyped this allele in populations who did not have disease or conditions directly related to UGT1A1 function (e.g., hyperbilirubinemia)." (PMID 32019188, 2020). "This shows that UGT1A1*6 is not prevalent, and that it is not a contributing factor toward the severity of hyperbilirubinemia in Southeast Asian populations." (PMID 31440488, 2019). "Importantly, we found the UGT1A1 IC50 value for 2,3-dehydrosilybin A even lower than that reported for atazanavir (2.3 μmol/L), the well-known hyperbilirubinemia-inducing drug indicating the high bilirubinemia-enhancing potential of this flavonolignan." (PMID 30891115, 2019). "This study aims to determine the potential effects of liver-expressing UGT1A1 and SLCO1B polymorphic variants and their combined effects on mild non-hemolytic unconjugated hyperbilirubinemia." (PMID 31737051, 2019). "Although human neonates physiologically develop mild hyperbilirubinemia, called jaundice, such a phenotype is not observed in other mammals such as mice or rats due to their extremely high UGT1A1 activity during the neonatal period." (PMID 26147428, 2015). "To study bilirubin toxicity in vivo, we generated a mutant mouse model of neonatal hyperbilirubinemia lacking Ugt1a1 enzyme activity." (PMID 25062689, 2014). "Owing to the lack of Ugt1a1 activity, homozygous mutant mice developed hyperbilirubinemia within 36 hours after birth, as evident by the yellow staining of their skin, as already reported." (PMID 25062689, 2014). "We suggest conducting a genetic analysis of UGT1A1 for patients experiencing chemotherapy-induced hyperbilirubinemia without any signs of liver dysfunction to avoid unnecessary changes in chemotherapy that could increase the risk of relapse." (PMID 39996891, 2025). "UGT1A1 is predominantly expressed in the liver, and genetic testing for UGT1A1 mutations is used to confirm diagnoses of GS, CNS2, or CNS1 in patients with persistent unconjugated hyperbilirubinemia without hemolysis." (PMID 39456788, 2024). "We speculate that because of some compensatory mechanism in the family described herein, down-regulated UGT1A1 isoenzyme activity was not consistent with unconjugated hyperbilirubinemia." (PMID 36274106, 2023).